TNF (tumor necrosis factor)
Diseases named in the same sentence as TNF in open-access papers (continued):
Sharing a sentence is not in itself a finding about the gene and the disease.
tumor (continued). "M1 can enhance the expression of MHC-II+, TNF-a, IL-1β, and IL-6, enhance the production of reactive oxygen species and NO, and have certain tumor damage activity." (PMID 39351151, 2024). "Several cytokines, including TNF-α, IL-10, IL-17, and IL-1β, have been shown to play an important role in the tumor inflammatory environment or tumor immune response." (PMID 38734702, 2024). "The expression of tumor cell-killing factors such as interferon-γ, tumor necrosis factor-α, and granzyme B by T cells was significantly increased, resulting in enhanced tumor cell killing." (PMID 38560505, 2024). "Modest quantities of TNF-α seem to increase the permeability of cancerous blood vessels, enhancing the tissue penetration of chemotherapy drugs and disrupting tumor angiogenesis." (PMID 39830670, 2024). "This strengthens our finding that elevated Zn intake suppresses IFN-γ and TNF-α in tumor-bearing mice." (PMID 39247196, 2024). "These therapeutic effects were associated with increased CD4+ and CD8+ T cells, and IFN-γ and TNF-α in tumor tissues, indicating that CMFn@OXA NPs induced a strong anti-tumor immune response." (PMID 39339217, 2024). "Enhancing macrophage innate immunity through co-culturing with tumor cells and large-scale genetic editing screening, utilizing TNF-α to validate innate immune functions, is critical." (PMID 39538305, 2024). "The influx of mast cells into TME is mediated by tumor-cell-released chemoattractants, such as SCF or CCL15, and then mast cells can actively participate in the elimination of tumor cells through secreted histamin, TNF-α, and IL-1, IL-4 and IL-6." (PMID 38287290, 2024). "In preclinical studies, this principle was initially introduced by the combination of a tumor stroma-directed immunocytokine with TNF (L19-TNF) and a RIPK1 inhibitor (GSK’963)." (PMID 38448542, 2024). "The activation of macrophages in response to M1 stimuli, like TLR ligands, IL-1β, or TNF-α, as well as the transcription of various tumor-promoting genes, including VEGF, IL-6, and COX2, is primarily regulated by NF-κB." (PMID 39003350, 2024). "This persistent inflammatory state in the TME contributes to tumor-supportive processes, including angiogenesis, invasion, and metastasis, which are often mediated by cytokines such as IL-6, TNF-α, and chemokines like CXCL8." (PMID 39769051, 2024). "Conversely, TNFα, which was originally named based on its direct cytotoxic activity on tumor cells, has been shown to participate in both the initiation and progression of cancer." (PMID 39204319, 2024). "In cases without apparent mutations, the activation of the pathway in tumor cells often stems from an increase in factors that induce activation of the pathway’s upstream receptors—such as cytokines like IL-6, TNFα, and IL-1—within the tumor microenvironment." (PMID 38331871, 2024). "In cancer patients, an elevated level of PCT is associated with the tumor microenvironment, characterized by an inflammatory state where tumor cells and surrounding cells produce proinflammatory mediators such as TNF-α, IL-6, and IL-1." (PMID 39797227, 2024). "MiRNA-509 (miR-509) prevents this action by suppressing the levels of TNF-α regulated in the tumor environment." (PMID 38726321, 2024). "Specifically, fermented milk inhibited breast cancer cell proliferation, reduced tumor size, and modulated cytokines (downregulated IL-6 levels and upregulated TNF-α, IL-4, and IL-10 levels)." (PMID 39605907, 2024). "This immunosuppressive environment is controlled by the tumor through the release of cytokines and other soluble factors such as TNF-α, IL-6, TGF-β, and IL-10, involved in cancer progression." (PMID 39247827, 2024). "They enhance the anti-tumor immune response by releasing cytokines, such as tumor necrosis factor-alpha (TNF-α) and interferon-gamma (IFN-γ)." (PMID 38720149, 2024). "The TNF signaling pathway mediates hematopoiesis, immune surveillance, tumor regression and infection prevention." (PMID 38702611, 2024).
tumor (continued). "Studies have shown that the N1 neutrophil phenotype is associated with high expression of Fas, TNF-α, and ICAM-1, typically accompanied by elevated infiltration levels of CD8+ T cells and NK cells, thereby enhancing anti-tumor immune responses." (PMID 39648199, 2024). "Pretreatment of a mesothelial cell monolayer with TNF enhanced the adhesion of tumor cells, with clear further enhancement by combined TNF/IL‐17A treatment." (PMID 38566518, 2024). "In TC, it was clear that the body responds to the tumor burden drastically both locally and systemically via the release of different immunosuppressive cytokines and markers such as IL-10, TNF-α, and iNOS which further support the tumor progression." (PMID 37612575, 2024). "Mechanically, TAMs interact with bone marrow stromal cells(BMSCs) to acquire the function of secreting IL-6 and IL-10, poorly secreting IL-12 and TNF-α, which are suitable for tumor growth." (PMID 38464531, 2024). "Lymphocytes secrete interferon‐gamma (IFN‐γ) and tumor necrosis factor-alpha (TNF-α) which are very important for inducing cytotoxic cell death and inhibiting tumor proliferation and tumor migration." (PMID 38910770, 2024). "Consistently, tumor-infiltrating CD8+ T cells with p16 overexpression demonstrated reduced frequency of TNF-α+IFN-γ+ population, indicating that p16OE impaired CD8+ T cell effector function at the tumor site." (PMID 38750022, 2024). "When appropriately stimulated, myeloid cells can differentiate into pro-inflammatory cells that have the potential to kill tumor cells via the production of cytokines such as TNF, phagocytosis or participation in antibody-dependent cytotoxicity." (PMID 39735543, 2024). "In vivo results showed that after 20 days of gavage administration of SNLP‐1 (4 mg/kg/day), macrophages in the LLC tumor model mice significantly down‐regulated NO, TNF‐α, and IL‐6, reducing tumor volume and weight." (PMID 39155844, 2024). "The proinflammatory cytokine TNF-α, produced by immune cells including T-cells, B-cells and macrophages, plays a complex role in neoplastic diseases." (PMID 39605908, 2024). "Specifically, within the tumor microenvironment, Fg γ390-396A’s interaction with leukocyte integrin αMβ2 not only enhances the secretion of pro-inflammatory cytokines like IL-6, IL-1β, IFN-γ, and TNF-α but also promotes tumor cell proliferation." (PMID 38779081, 2024). "M1 macrophages are considered to be "tumor killer macrophages", secreting pro-inflammatory cytokines, including IL-12, TNF-α, etc., mainly anti-tumor and promote immunity." (PMID 38688945, 2024). "M1-like macrophages can kill invading pathogens and tumor cells by secreting proinflammatory cytokines, including interleukin (IL)-12p40 and tumor necrosis factor-α (TNF-α) 9-11." (PMID 38250157, 2024). "Histological observations suggested a concurrent red blood cell influx and increased pro-inflammatory cytokine production, particularly Tumour Necrosis Factor (TNF)-α, that washed bacteria into the tumours from the vasculature." (PMID 39272829, 2024). "In the T cells generated via PBNP‐PTT, both CD8+ effector T cells (39.2 ± 2.1%) and effector memory T cells (14.8 ± 6.6%) produced IFNγ and TNFα in response to target U87 cells, suggesting tumor‐specific activation." (PMID 38818122, 2024). "Reverse transcription and quantitative polymerase chain reaction (RT-qPCR) analysis of gene expression for cytokines related to tumor progression confirmed that TNF mRNA abundance was increased specifically in PC9/p53GOF cells treated with osimertinib." (PMID 38431700, 2024). "On the other hand, IFN-γ-induced protein 10 (IP-10), induced by IFN-γ and up-regulated in response to inflammatory cytokines, including TNF-α, was shown to act in an autocrine fashion to improve tumor cell proliferation, angiogenesis, and metastasis." (PMID 38954024, 2024).
tumor (continued). "In lung cancer, PGD2 acts as an anti-tumor angiogenic factor and limits the further development of tumors by restricting the expression of some pro-angiogenic factors such as TNF-α and VEGF." (PMID 38704736, 2024). "M1 macrophages, in turn, secrete pro-inflammatory cytokines, such as IL-6, IL-12, and TNF-α, further leading to Th1 polarization and anti-tumor effects." (PMID 38339310, 2024). "In line, blocking tumor-associated macrophages which decreases TNFα and elevates IL33 resulted in increased DC activity and infiltration of cytotoxic T cells, with anti-tumor activity." (PMID 38942797, 2024). "Tumor necrosis factor-α (TNFα), secreted by both tumor cells and bone marrow stromal cells, has a dual effect, promoting osteoclast differentiation while inhibiting osteoblast function." (PMID 38474093, 2024). "Deleting CBL-B in CAR-T cells leads to increased expression of IFN-γ and TNF-α, thereby enhancing their tumor-killing abilities." (PMID 39223632, 2024). "The persistent secretion of TNF-α by both tumor cells and the local microenvironment has the potential to enhance the growth and spread of BRCA." (PMID 39342122, 2024). "Interleukin-6 (IL-6), interleukin-1 (IL-1), and TNF-α, among others, are produced by tumor cells and stromal cells." (PMID 38612357, 2024). "TNF-α induces the release of other cytokines, thus creating a tumor microenvironment that favors the proliferation and survival of malignant cells." (PMID 38473882, 2024). "Continuous stimulation of sgRNA-transduced tumor cells with IFN-γ or TNF allows for the identification of regulatory factors that are sensitive or resistant to these cytokine pathways, based on the survival of the tumor cells." (PMID 39538305, 2024). "Our single-cell RNA sequencing analyses revealed enrichment of ONECUT2-positive tumor cells within clusters displaying TNFα signaling via NFκB." (PMID 38997271, 2024). "Mechanistically, tumour necrosis factor alpha (TNFα)-regulated PGLYRP1 expression interferes with the immune tumour microenvironment (TME) landscape, promoting myeloid cell-derived immunosuppression and activated T-cell death." (PMID 38754953, 2024). "For instance, poly-γ-glutamic acid-based platforms with chitosan have enhanced cytokine secretion by macrophages, increasing IL-6, IL-12, and TNF-α levels, which inhibit tumor cell invasion." (PMID 39684867, 2024). "Firstly, TNF-α enhances the effectiveness of liposome-mediated chemotherapy by increasing blood vessel permeability, thereby facilitating drug accumulation at the tumor site." (PMID 39605908, 2024). "Extracellular components include growth factors, chemical factors, pro-inflammatory cytokines, tumor necrosis factor, etc., which can all affect tumor cells." (PMID 39445018, 2024). "During early stages of tumorigenesis another cytokine is secreted and released into the TME: TNFα that has an established role in angiogenesis, chronic inflammation, tissue remodeling, tumor growth." (PMID 39015505, 2024). "It was discovered as a tumor necrosis factor and named due to its ability to induce the death of tumor cells." (PMID 38612709, 2024). "TAMs secrete a series of cytokines and inflammatory factors such as TGF-β), IL-6, IL-10, IL-13, IL-4 and TNF-α that promote tumour initiation, growth, metastasis, angiogenesis, proliferation and chemoresistance in HCC (Ref." (PMID 39320855, 2024). "The neutrophil-produced tumor necrosis factor (TNF) induces feed-forward CXCL1 overproduction in both tumor cells and CAFs, leading to T-cell suppression." (PMID 38339310, 2024). "The cytokines produced by activated T cells, such as interferon γ (IFN-γ) and tumor necrosis factor α (TNF-α), have the ability to up-regulate PD-L1 expression on tumor cells." (PMID 39635535, 2024). "In contrast to TAMs exhibiting an M2, pro-tumoral phenotype, M1 TAMs are classically associated with playing an anti-tumor role by secreting factors known to inhibit tumor growth, such as TNF-α, IL-1β, IL-6, IL-8, IL-12, and IL-23." (PMID 38893093, 2024).
tumor (continued). "Tumor-related proinflammatory cytokine secretion is one of the main mechanisms underlying CACS, in particular interleukin-1 (IL-1), interleukin-6 (IL-6), tumor necrosis factor alpha (TNF-α), and C-reactive protein (CRP)." (PMID 38822976, 2024). "recently demonstrated that tumour necrosis factor (TNF)‐α‐dependent lung inflammation can facilitate the upregulation of CD74 in tumour cells, promoting the proliferation and migration of LC cell lines." (PMID 39113235, 2024). "Platycodin D, a major component of Platycodon grandiflorum roots and a component of GJS, significantly inhibits tumor growth by increasing interferon-γ, TNF-α, IL-6, and IL-2 levels and improves immune function." (PMID 39273195, 2024). "Hepcidin silencing in combination with αPD-1 reduced the CT26-derived tumor growth significantly and enhanced the number of tumor-infiltrating TNF-secreting CD8+ T cells as compared to controls." (PMID 39682254, 2024). "We found that perforin, granzyme B, IFN-γ, and TNF-α were unevenly distributed within the tumor, showing that these were three pathways to induce activation of N-GSDMD, N-GSDME, and cleaved-CASP3 by perforin, granzyme B, IFN-γ, and TNF-α." (PMID 38740747, 2024). "CD4+ T cells secrete different tumouricidal cytokines, such as interferon-γ (IFNγ) and TNFα to support CTLs in the disruption of primary tumour cells." (PMID 39000359, 2024). "Short-term, localized administration of TNF-α has been demonstrated to exhibit anti-tumor effects, whereas prolonged expression of TNF-α can lead to a pro-tumorigenic state." (PMID 38254110, 2024). "TNF-α, a pro-inflammatory cytokine, plays a critical role in mediating immune responses and influencing tumor microenvironment interactions." (PMID 39398744, 2024). "TNF-α has been described as a circulating factor that can lead to tumor necrosis and has been identified as a key regulator of inflammatory action." (PMID 38672467, 2024). "The dominance of pro-inflammatory mediators such as IL-11β, TNF-α and IL-6 over anti-inflammatory mediators such as TGF-β and IL-10 has been implicated in tumor progression." (PMID 39682161, 2024). "Functionally, the CD19 CAR-UiNK cells robustly secreted IFN-γ and TNF-α, and upregulated CD107a upon stimulation with Nalm-6 tumor cells." (PMID 39664387, 2024). "Inflammatory cytokines, such as interleukin (IL)-1, IL-6, IL-10, tumor necrosis factor-α, macrophage migration inhibitory factor, and transforming growth factor-β, are involved in tumor initiation and progression." (PMID 38267838, 2024). "BMSCs contribute to the pro-inflammatory tumor microenvironment by expressing key factors such as IL-1β, TNFα, LIF, and COX2, which support MM proliferation." (PMID 39609411, 2024). "TNF-α has tumor necrosis activity; IL-1β attracts neutrophils and causes the release of inflammatory mediators, which promotes the expression of vascular leukocyte adhesion molecules and induces inflammatory responses." (PMID 39063304, 2024). "Extracellular secretion of cytokines, such as IL1β or TNFα, and lymphokines is noticeable in the tumor stroma, as well as the presence of growth factor VEGF-A, which is linked to tumor blood vessel formation." (PMID 39625899, 2024). "For example, the pro-inflammatory factors TNF-α, IL-6, and IL-1β promote tumor growth, invasion, and metastasis." (PMID 38368407, 2024). "Existing literature analysis revealed a simultaneous upregulation in TNF-α, IL-6, and IL-1β expression in tumor-bearing mice's hippocampus at that same time point, with mRNA levels aligning with observed plasma cytokine increases." (PMID 39286150, 2024). "For instance, experimental studies have shown that sleep deprivation in animal models leads to increased levels of pro-inflammatory cytokines like IL-6 and TNF-α, which can suppress immune surveillance and promote tumor growth." (PMID 39120277, 2024).
tumor (continued). "In tumors, they are classified into two phenotypes: an N1 neutrophil phenotype with anti-tumor activity, which induces direct or indirect cytotoxicity by producing TNF-α, CCL3 and expressing ICAM-1." (PMID 39179536, 2024). "T helper (Th) cells play a crucial role in enhancing anti-tumor and anti-inflammatory immune responses by releasing various cytokines such as TNF-α, Granulocyte-Macrophage Colony-Stimulating Factor (GM-CSF), IL-2, IL-6, IL-10, IL-21, and others." (PMID 38755133, 2024). "It is true that high dose of TNF can kill cancer but at the low level it will promote tumor development." (PMID 38800967, 2024). "Flow cytometry confirmed increased IFN-γ and tumor necrosis factor α production in tumor-infiltrating CD8+ T cells in response to combination therapy compared to control, suggesting enhanced effector function." (PMID 38518770, 2024). "Macrophages are usually converted to M1-like TAMs after the action of IFNγ, and TNFα, as well as lipopolysaccharides to exert tumor suppressive effects." (PMID 39776907, 2024). "Tumours enriched with inflammatory genes, particularly in IFN- and TNF-α-related pathways and CD4+ T cells in an inflamed tumour microenvironment, were associated with better response to chemotherapy." (PMID 39409156, 2024). "In the tumor microenvironment, large amounts of pro-inflammatory cytokines, such as interleukin-6 (IL-6) and tumor necrosis factor-α (TNF-α), are secreted." (PMID 39687887, 2024). "But CD44+OT-ICD8+T cells produced higher levels of IFN-γ and TNF-α, and slightly reduced tumor volume." (PMID 38279145, 2024). "Myeloid-derived growth factor promotes chemotaxis of macrophages into tumor tissues, enhancing their release of inflammatory cytokines such as IL-6 and TNF-α." (PMID 39068459, 2024). "Stimulation of the CD40/CD40L axis destroys tumor cells by stimulating CD8 T lymphocytes with TNF-α; conversely, it suppresses immunity by stimulating TNF-β production and causing a tumorigenic effect." (PMID 39625893, 2024). "Tumor tissues from these mice showed increased mature dendritic, CD4+ T, and CD8+ T cells and pro-inflammatory cytokines (IFNγ and TNFα) and decreased regulatory T cells, and the expression of tumor cell proliferation markers (Ki67 and CD31) was downregulated." (PMID 38323311, 2024). "Proinflammatory cytokines, including IL‐8, MIF, and TNF‐α, were significantly upregulated in tumor tissues." (PMID 38041547, 2024). "M1-type TAMs secrete anti-angiogenic factors like IL-12 and TNF-α to inhibit tumor angiogenesis and promote blood vessel maturation, and reducing the vascular density in the tumor suppresses tumor growth and development." (PMID 39691707, 2024). "IL-6 and TNF-α were chosen as inflammatory indicators to evaluate the changes in the tumor microenvironment." (PMID 39065602, 2024). "Subsequently, M1 macrophages eliminate tumor cells by releasing NO, IL-12, IL-23, TNF-α, IL-6 and ROS." (PMID 38792234, 2024). "When LPS binds to TLR4 in gastric epithelial cells, TLR4 signaling is activated, which leads to the production of inflammatory mediators including IL-8 and TNF-α, which are essential for the progression of tumor." (PMID 39035439, 2024). "Tumor necrosis factor and interleukin-6 released by the tumor and surrounding cells can suppress protein synthesis and stimulate protein degradation." (PMID 38913646, 2024). "It was also demonstrated that tumor growth was followed by its infiltration by macrophages that synthesize TNFα." (PMID 39063041, 2024). "The anti-tumor effects are enhanced by the secretion of CD8+ T lymphocyte factors TNF-α, IFN-γ, and granzyme B, which is promoted by the knockdown of NEAT." (PMID 39346921, 2024). "In contrast to CD47, TNF-α induced an increase in PD-L1 expression on tumor cells, however, the level was comparable to that seen on the iTCS-treated MSCs." (PMID 39310770, 2024). "The inflammatory tumor microenvironment is orchestrated by cytokines such as IL-6, IL-1β, TNF-α, and IL-23." (PMID 39766123, 2024).